STRADA (STE20 related adaptor alpha)
Description:
Pseudokinase which, in complex with CAB39/MO25 (CAB39/MO25alpha or CAB39L/MO25beta), binds to and activates STK11/LKB1. Adopts a closed conformation typical of active protein kinases and binds STK11/LKB1 as a pseudosubstrate, promoting conformational change of STK11/LKB1 in an active conformation.
Synonyms: STRAD alpha; LYK5; STRAD; STLK5; NY-BR-96; Stlk; PMSE
Tractability: Small molecule: a structure with a bound ligand is known; a high-quality ligand is known; it has a high-quality binding pocket. PROTAC: ubiquitination databases record sites on it; its protein half-life has been measured; a small molecule that binds it is known.
Gene: Protein-coding gene on chromosome 17 (63,682,336 to 63,741,986, reverse strand). Ensembl gene ENSG00000266173.
Subcellular location: Nucleus; Cytoplasm
Subcellular location (Human Protein Atlas): Cytosol; Nucleoplasm
Pathways (Reactome):
Signal Transduction: Energy dependent regulation of mTOR by LKB1-AMPK
Gene Ontology:
Molecular function: kinase binding; protein binding; protein kinase activator activity; protein kinase activity; protein serine/threonine kinase activator activity; ATP binding
Biological process: activation of protein kinase activity; G1 to G0 transition; protein export from nucleus; protein phosphorylation
Cellular component: cytoplasm; cytosol; intracellular protein-containing complex; nucleoplasm; nucleus; serine/threonine protein kinase complex
Genetic constraint (gnomAD): Loss-of-function variants: 26 observed, 55.62 expected, observed/expected ratio (o/e) 0.47, 90% interval 0.34 to 0.65. The upper end of that interval is the gene's LOEUF score, 0.65, which puts it in group 2 of 6, group 1 being the genes least tolerant of losing a copy. Missense variants: 443 observed, 568.37 expected, observed/expected ratio (o/e) 0.78, 90% interval 0.72 to 0.84. Synonymous variants: 197 observed, 220.74 expected, observed/expected ratio (o/e) 0.89, 90% interval 0.79 to 1.
Homologues: Orthologues: chimpanzee STRADA (99% identical), macaque STRADA (99% identical), dog STRADA (97% identical), pig STRADA (96% identical), mouse Strada (95% identical), guinea pig STRADA (94% identical), rabbit STRADA (86% identical), rat Strada (86% identical), tropical clawed frog strada (72% identical), zebrafish strada (62% identical). Paralogues in human: STRADB (42% identical), OXSR1 (27% identical), STK39 (26% identical), MAP4K3 (24% identical), MAP4K4 (24% identical), MAP4K5 (24% identical), STK25 (24% identical), TNIK (24% identical), MAP4K1 (24% identical), PAK3 (24% identical), STK24 (23% identical), STK26 (23% identical), and 23 more.
Diseases named in the same sentence as STRADA in open-access papers:
STRADA is named in the same sentence as 26 diseases in open-access papers, as found by Europe PMC text mining. Sharing a sentence is not in itself a finding about the gene and the disease. The quoted sentences say what the papers report.
epilepsy (10 papers, 2009 to 2023). A brain disorder characterized by episodes of abnormally increased neuronal discharge resulting in transient episodes of sensory or motor neurological dysfunction, or psychic dysfunction. "Future studies should focus on the downstream consequences of STRADA loss to uncover epilepsy mechanisms in PS that would likely apply to other mTORopathies and lead to the development of novel therapies." (PMID 32457579, 2020). "Patients with homozygous recessive STRADα mutations develop polyhydramnios, megalencephaly, and symptomatic epilepsy (PMSE)." (PMID 24225308, 2013). "It has recently been demonstrated that a mutation in human STRADα that truncates a C-terminal region of the pseudokinase domain leads to the polyhydramnios, megalencephaly, symptomatic epilepsy (PMSE) syndrome." (PMID 19513107, 2009). "Polyhydramnios, megalencephaly and symptomatic epilepsy (PMSE) has shown to be having a deletion in STRADα gene, which regulates AMPK, an energy-sensor protein kinase that controls mTORC1 and TSC229." (PMID 30568293, 2018). "While little is known about STRADβ function, homozygous deletion within the human LYK5 (STRADα) locus results in a syndromic condition known as polyhydramnios, megalencephaly, and symptomatic epilepsy (PMSE)." (PMID 24594058, 2014). "For instance, in TSC, DEPDC5 or STRADA related seizure disorders, mTORC1 is hyperactive and mTORC2 activity is often reduced or unchanged, indicating that mTORC1 may be the major driver." (PMID 37963879, 2023). "Mutations in STRADA, SYNJ1, CACNA1A and NPRL3 have also been reported with severe epilepsy-related disease, but the association has not been reported for heterozygous variants in isolated forms of epilepsy." (PMID 36539902, 2022). "Recently, it was reported that a severe human developmental and epileptic syndrome termed polyhydramnios, megalencephaly, symptomatic epilepsy (PMSE), was caused by a homozygous partial deletion in the STRADα gene (LYK5), truncating 180 C-terminal residues of the protein." (PMID 19513107, 2009).
polyhydramnios, megalencephaly, and symptomatic epilepsy (8 papers, 2009 to 2025). A syndrome characterized by polyhydramnios, distinctive craniofacial features, infantile-onset epilepsy, hypotonia, macrocephaly, and global developmental delay that has material basis in homozygous mutation in the STRADA gene on chromosome 17q23.3. "Our results also indicate that the human mutation that causes PMSE syndrome destabilizes STRADα and prevents it from binding to, and activating LKB1." (PMID 19513107, 2009). "Polyhydramnios, megalencephaly, and symptomatic epilepsy syndrome (PMSE or Pretzel syndrome) is an ultra-rare neurodevelopmental disorder caused by variants in the LYK5/STRADA gene." (PMID 40426219, 2025). "PMSE syndrome, also known as Pretzel Syndrome, is caused by a homozygous truncating germline mutation in the STE20-related kinase adaptor alpha (STRADA) gene, an upstream regulator of mTORC1." (PMID 40358185, 2025). "Further studies identified a role of bRG in the pathogenesis of Pretzel syndrome (polyhydramnios, megalencephaly, symptomatic epilepsy; PMSE) derived from mutations in the STRADA gene, part of the mTOR pathway." (PMID 35774229, 2022).
glioblastoma (1 paper, 2010). The most malignant astrocytic tumor (WHO grade IV). "Of particular interest was the specific expression of ATP6v0A1, STRADA, PCNP and CS transcript variants, analyzed in patients affected by glioblastoma, which confirmed all the predicted cassette exons, thus demonstrating the reliability of our computational analysis." (PMID 20813049, 2010). "The validation of the cassette exons specific for the nervous system, detected for ATP6v0A1, STRADA, PCNP and CS genes, prompted us to analyze their expression in patients affected by glioblastoma, the most frequent form of primary intracranial malignancy." (PMID 20813049, 2010).
muscular dystrophy (1 paper, 2023). Muscular dystrophy (MD) refers to a group of more than 30 genetic diseases characterized by progressive weakness and degeneration of the skeletal muscles that control movement. "Notably, a similar extent of LKB1 downregulation and low levels of MO25 and STRADα were found in the D2 mdx mouse model, supporting the overall impairment of the heterotrimeric complex as a key feature of muscular dystrophy." (PMID 37427454, 2023).
neuroblastoma (1 paper, 2010). Neuroblastoma (NB) is the most common solid, extracranial childhood tumor. "Notably, we compared the presence of the specific cassette exons in RNA from normal brain and neuroblastoma (for ATP6v0A1, STRADA, PCNP and CS) and from skeletal muscle and rhabdomyosarcoma (for TPM3, TPD52L2, NAP1L1, METT10 D and SLC25A3)." (PMID 20813049, 2010).
osteoporosis (1 paper, 2023). A condition of reduced bone mass, with decreased cortical thickness and a decrease in the number and size of the trabeculae of cancellous bone (but normal chemical composition), resulting in increased fracture incidence. "In addition, a relationship between STRADA and STK11 overexpression in glucocorticoid-induced osteoporosis was described." (PMID 36833439, 2023).
ovarian carcinoma (1 paper, 2024). A malignant neoplasm originating from the surface ovarian epithelium. "Since matrix metalloproteinase 9 (MMP9) and MMP2 are upregulated in ovarian cancer and their activity is correlated with invasion and metastasis, we hypothesized that the impact of LKB1 and STRADα on EOC invasion is mediated by MMP activity." (PMID 39594681, 2024).
prostate carcinoma (1 paper, 2012). A carcinoma that arises from epithelial cells of the prostate gland. "Our finding that STRADA exhibited reduced expression in a large percent of human prostate cancers is consistent with a tumor suppressor role." (PMID 22509301, 2012). "The potential role of STRADA in prostate cancer progression and the possibility of LKB1/AMPK-independent functions warrant additional attention." (PMID 22509301, 2012). "We identified and validated four candidate genes (AKT1, PSMC1, STRADA, and TTK) that impaired growth when silenced in androgen receptor positive prostate cancer cells and enhanced the antiproliferative effects of antiandrogens." (PMID 22509301, 2012). "To explore whether AKT1, STRADA, and TTK are altered in human prostate cancer, we assessed the copy number and expression status of these genes in a previously-reported human prostate cancer dataset." (PMID 22509301, 2012).
prostate tumors (1 paper, 2012). "The large number of prostate tumors with alterations in STRADA, TTK, and AKT1 expression led us to look at their correlation with biochemical recurrence." (PMID 22509301, 2012). "Of the 218 prostate tumors, 34.4% had reduced expression of STRADA, 18.3% exhibited overexpression of TTK, 11.7% either overexpressed or had reduced expression of AKT1, and 15.6% of tumors overexpressed or had amplified AR." (PMID 22509301, 2012). "Unlike AR, STRADA, TTK, and AKT1 showed little evidence of gene amplification or loss in human prostate tumors." (PMID 22509301, 2012).
tumor (15 papers, 2009 to 2024). "STRADA is required for function of the LKB1 tumor suppressor; therefore, silencing of STRADA might be expected to promote tumorigenesis." (PMID 22509301, 2012). "The second process where we observed that intact LKB1 and STRADα expressions were required for EOC spheroid cell invasion was fibronectin production, which is known to serve as an ECM scaffold for invading tumor cells." (PMID 39594681, 2024). "The pseudokinase domain of STRADα directly interacts with the kinase domain of LKB1, thus triggering the activation of LKB1’s tumor-suppressing phosphotransferase functions." (PMID 39088265, 2024). "Thus, the tumor suppressor activity linked to LKB1 kinase activity could be acquired through STRADα-dependent (LKB1G135R and LKB1D194Y) or STRADα-independent mechanisms (LKB1Y49D); the later also affect the subcellular localization and most likely other processes, such as transcriptional regulation." (PMID 32647375, 2020). "For example, the pseudokinase STRADα regulates LKB1, a S/T protein kinase that regulates AMP activated kinase and acts as a tumor suppressor." (PMID 23144612, 2012). "The conformation of the pseudokinase STRADα, which is regulated by binding to ATP and to the scaffolding protein MO25α, is key to the activiation of the LKB1 tumor suppressor complex." (PMID 19513107, 2009). "However, besides to the presence of STRADα, LKB1Y49D showed a mainly nuclear localization in the three different cell lines tumor models (A549, HeLa, and G361), suggesting a lack of binding of this isoform to STRADα." (PMID 32647375, 2020).
cancer (6 papers, 2010 to 2025). A tumor composed of atypical neoplastic, often pleomorphic cells that invade other tissues. "In particular, the cassette exons we identified in the STRADA gene represent a very promising biomarker as their significant differential expression in the normal and cancer conditions is homogeneously conserved in all samples analyzed." (PMID 20813049, 2010). "One group identified STRADα as a regulator of Caenorhabditis elegans cell polarity, and another found that STRAD participates in cancer cell polarity and migration in LKB1-null cells." (PMID 39594681, 2024). "CAB39, a component of a trimeric complex including serine/threonine kinase 11 (STK11) and STE20-related adaptor alpha (STRAD), has been studied in the context of cancer progression, but with unknown function during SARS-CoV-2 infection." (PMID 40833112, 2025).
neurodevelopmental disorder (3 papers, 2017 to 2025). A behavioral and cognitive disorder with onset during the developmental period that involves impaired or aberrant development of intellectual, motor, or social functions. "Several mutations in mTOR regulatory genes (e.g., TSC1, TSC2, LYK5/STRADA, AKT3, and DEPDC5) enhance activation of mTOR and lead to brain malformation and neurodevelopmental disorders." (PMID 29259984, 2017).
STRADA also shares sentences with these, for which no sentence is quoted: Polyhydramnios (4 papers); breast carcinoma (3); megalencephaly (3); infection (2); bacterial infection (1); developmental delay (1); fungal infection (1); gastric cancer (1); hypertrophic cardiomyopathy (1); Intellectual disability (1); medulloblastoma (1); pancreatic cancer (1); paroxysmal AF (1); rhabdomyosarcoma (1).